PCNA (proliferating cell nuclear antigen)
Diseases named in the same sentence as PCNA in open-access papers (continued):
Sharing a sentence is not in itself a finding about the gene and the disease.
cancer (continued). "However, longer incubation of WHCO1 and MDA MB 231 cells with WJ-MSCs did not result in sustained downregulation of PCNA, BCL-2, MMP-2, and c-MYC gene expression in the cancer cells indicating that the effect of coculture is transient." (PMID 26880967, 2016). "Another study with patient-derived organoids model revealed that the oligomeric proanthocyanidins combined to the curcumin attenuated the expression of cyclin D1, PCNA, and HSPA 5, which could serve as a method that preferentially targets cancer cells without affecting normal cells." (PMID 36776331, 2023).
infection (60 papers, 2011 to 2026). The state of being infected such as from the introduction of a foreign agent such as serum, vaccine, antigenic substance or organism. "Infection amplifies the expression of Proliferating Cell Nuclear Antigen (PCNA), a protein implicated in DNA damage repair and prevention." (PMID 38188016, 2023). "Because agnoprotein expression occurs at a later stage of the infection cycle, it is more probable to assume that agnoprotein suppresses viral DNA replication by perturbing PCNA’s function and allowing assembly of virions." (PMID 25638270, 2015). "Compared to the NTC, USP1 depletion in WT infection led to a modest, but significant, increase in mUb–PCNA and mUb–FANCD2 at 48 hpi and 72 hpi, respectively, resembling the phenotype observed in ∆UL138STOP infection." (PMID 41533576, 2026). "HCMV pUL48 has DUB activity; however, a role for pUL48 or host DUBs in deubiquitinating PCNA during infection has yet to be defined." (PMID 40130902, 2025). "HBV+DEN-treated Il33KO, ST2KO, and Irf3KO mice showed significantly lower liver tumor burden and decreased PCNA+ proliferating hepatocytes compared with HBV+DEN-treated WT mice at 8 months post-infection." (PMID 40579434, 2025). "To build upon our finding that PCNA restricts HCMV TB40/E replication, we sought to determine the significance of mUb-PCNA during infection." (PMID 40130902, 2025). "While we observe that PCNA restricts viral genome synthesis in low MOI infections of TB40/E, it is possible that strain differences account for the discrepancy in results." (PMID 40130902, 2025). "Consistent with this, we also measured viral genome copy number at 15 days post-infection and observed an increase with depletion of PCNA." (PMID 40130902, 2025). "Taken together, these data suggest that the restriction imposed by PCNA on vDNA synthesis is reflected in reduced viral gene expression late in infection." (PMID 40130902, 2025). "HBV+DEN-treated TregST2CKO mice showed significantly lower liver tumor burden, improved liver architecture, and decreased PCNA+ proliferating hepatocytes compared with HBV+DEN-treated WT mice at 8 months post-infection." (PMID 40579434, 2025). "HCMV-infected cells accumulated mUb-PCNA as infection progressed, consistent with previous findings, while levels did not change in PAA-treated cells (quantified in 1C)." (PMID 40130902, 2025). "We limited our analysis to markers of late stage infection, including PCNA, which accumulates within nuclear replication compartments, and Cyclin B–Cdk1, which contributes to virion egress." (PMID 39655950, 2025). "Building on the findings presented here, we sought to determine if depletion of PCNA alone was sufficient to compromise viral genome integrity in HCMV TB40/E infection and if genome integrity depended on modification at K164." (PMID 40130902, 2025). "We find that mUb-PCNA increases over the course of infection, and modification of K164 is required for PCNA-mediated restriction of virus replication." (PMID 40130902, 2025). "Cells depleted of PCNA infected at a multiplicity of infection (MOI) of 1 and collected over a 96-hour time course exhibited a fourfold increase in viral titers but no significant increase in viral genomes." (PMID 40130902, 2025). "To verify if our findings concerning M protein and the DNA damage markers PCNA and γH2AX were also reproducible during infection, we evaluated the effect of SARS-CoV-2 infection in Vero E6 cells." (PMID 35677658, 2022). "Compared with the infection group, the levels of PCNA in the JYBR-190 pre-fed, JYBR-190 fed, and antibiotic groups were significantly increased." (PMID 35692296, 2022). "Compared with the CON group, NE infection reduced the numbers of PCNA-positive cells in the ileum, indicating remarkable inhibition of proliferation following NE infection." (PMID 35387091, 2022).
infection (continued). "The expression levels of PCNA in the duodenum, jejunum and cecum showed that compared with the blank control group, the expression level of PCNA in the infection group was significantly lower." (PMID 35692296, 2022). "The effect observed during infection is a higher expression of PCNA and phosphorylation of histone H2AX in both cell lines." (PMID 35677658, 2022). "Quantification of dissociated retinal organoids confirmed that percentages of GFP+PCNA+ double labeled cells were reduced significantly from 52.7 ± 8.0% for LV-GFP infection to 9.0 ± 3.8% and 2.0 ± 1.9% for LV-AEP and LV-NEP infections, respectively." (PMID 34055784, 2021). "Proliferating cell nuclear antigen (PCNA) is another interacting partner of BKV agnoprotein which inhibits viral DNA replication during the late stages of infection when virion assembly occurs." (PMID 34834972, 2021). "Compared with the SIV− group, long-term SIVmac239 infection induced obvious decreases in the number of differentiated SSCs (defined by c-kit expression) and proliferating cells (defined by PCNA expression)." (PMID 34630335, 2021). "Here, we demonstrate that T. gondii extends the life span of human peripheral blood neutrophils during infection by inducing the expression of proliferating cell nuclear antigen (PCNA), a key inhibitor of apoptotic caspases." (PMID 33500339, 2021). "We estimated the nuclear PCNA abundance during 24 h of in vitro infection using immunostaining and calculated PCNA signal intensity relative to the host cell nucleus (DAPI signal)." (PMID 32548739, 2020). "We found that the recruitment of PCNA onto the cccDNA was most stable at 11 days post infection, indicating that PCNA is able to anchor onto cccDNA minichromosome." (PMID 31410212, 2019). "At 24 hours after infection, levels of all three transcripts were elevated in dl309 infected cells, and they continued to increase with the exception of PCNA mRNA, which was reduced at 72 hours after infection as compared to 24 hours." (PMID 26448631, 2015). "We have also observed that PCNA mRNA levels decrease at 72 hours after infection, perhaps due to the same reasons as the observed early expression of PCNA during the infection." (PMID 26448631, 2015). "Expression of BLM, MCM4, and PCNA was unaltered at 8 hours after infection as compared to mock-infected cells." (PMID 26448631, 2015). "Similar to the p21ΔDegron mutant, the p21K7R protein was resistant to degradation following MVM infection (compare lanes 6 and 8 to 2 and 4), yet retained substantial interaction with PCNA in transient transfection assays (compare lane 3 to lanes 2 and 4)." (PMID 24699724, 2014). "Using inducible cell lines expressing wild-type and mutant p21 proteins we demonstrated that p21 degradation during infection required motifs that mediate interaction with both Cdt2 and PCNA." (PMID 24699724, 2014). "Western blotting showed increased PCNA expression from day8 (∼1.49-fold) to 180 (∼2.52-fold) which peaked at day90 (∼2.54-fold) post-infection; it then decreased to the baseline at days 270 (∼1.33-fold) and 360 (∼1.19-fold)." (PMID 22253905, 2012). "Using flow cytometric analyses, microglia increase expression of the nuclear cell-cycle protein, PCNA in response to TMEV infection with peak expression observed at day 7 post-infection." (PMID 21494618, 2011). "Microglia upregulate PCNA expression as early as day 3 post-infection compared to microglia from sham-infected mice (13.75±3.35% vs. 7.13±2.47%) with the most significant increase observed at day 7 post-infection (35.07±2.56% vs. 14.05±4.85%)." (PMID 21494618, 2011). "Infection with H. pylori might increase the expression of proliferating cell nuclear antigen (PCNA) while simultaneously decreasing the expression of Bcl-2-associated X protein (Bax)." (PMID 40964055, 2025).
infection (continued). "Importantly, pitavastatin treatment significantly lowered liver tumor burden, improved liver architecture, and decreased PCNA+ proliferating hepatocytes compared with carrier control in HBV+DEN-treated WT mice at 8 months post-infection." (PMID 40579434, 2025). "In control-infection spheroids, T3 increased the percentage of PCNA-positive proliferating cells." (PMID 38693105, 2024). "Given the role of PCNA to prolong neutrophil survival and contribute to the neutrophil dominant states (infection or acute inflammation), it has been of increasing interest to explore the targeting of PCNA to reduce long term damage and the development of chronic inflammation." (PMID 39205238, 2024). "Additionally, the infection increased the expression of cyclin D1 and/or PCNA, critical regulators of proliferation, in cultures of smooth muscle cells and myocardial tissue in infected mice." (PMID 38188016, 2023). "Infection resulted in a trending increase in PCNA expression." (PMID 37966250, 2023). "However, with infection the further aggravation of the PCNA index indicates that the intestinal epithelial cells are damaged, accompanied by a gradual decline in the proliferative capacity." (PMID 35692296, 2022). "Infection of neutrophils resulted in increased interaction of PCNA with pro-caspase-3." (PMID 33500339, 2021). "Furthermore, the infection of HPV is significantly correlated with PCNA overexpression in LSCC patients." (PMID 24353714, 2013). "In addition, the expression level of hepatic DNA polymerase processivity factor proliferating cell nuclear antigen (PCNA), which serves as the master coordinator of DNA replication and repair, was enhanced upon S. mansoni infection, most significantly upon bs-infection." (PMID 37696392, 2024). "In addition to finding the upregulation of PCNA transcripts and a sustained increase in PCNA protein during infection of neutrophils, we found that T. gondii significantly increased the interaction between PCNA and pro-caspase-3 in the cytosol of human neutrophils." (PMID 33500339, 2021). "Interestingly, levels of PCNA mRNA were induced the least by pm975 infection at 24 hours." (PMID 26448631, 2015). "Mutation of the p21 PIP box (p21ΔPCNA) abrogated interaction with PCNA (compare lane 3 to 2), and the p21ΔPCNA protein expressed in murine cells was not degraded as efficiently as the wild-type protein (p21WT) following infection (compare lanes 8 and 6 to 4 and 2)." (PMID 24699724, 2014). "In the present study, we could confirm the induction of p-ERK1/2 and a parallel expression of Cyclin D1 and PCNA from the beginning of infection and their persistence during the progression of E. multilocularis growth in the liver during the first 2 stages of parasite development." (PMID 22253905, 2012). "The current study set out to determine whether a population of wild brown trout, Salmo trutta trutta (L.)harbouring an infection of the acanthocephalan Dentitruncus truttae Sinzar, 1955 collected from Lake Piediluco in Central Italy also effected changes in the expression of PCNA." (PMID 22967751, 2012). "UL138-UAF1–USP1 stimulates deubiquitination of PCNA and FANCD2 during infection with restrictive effects on viral genome synthesis." (PMID 41533576, 2026). "Compared to NTC, depletion of PCNA/FANCD2/FANCI or PCNA/FANCD2/FANCI combined with USP1 increased viral genome synthesis in WT and ∆UL138STOP infections." (PMID 41533576, 2026). "Here, we demonstrate that PCNA was relocalized to RCs between 24 and 72 hpi in CMV TB40/E infection." (PMID 41533576, 2026).
infection (continued). "PCNA and FANCD2 were also relocalized to RCs in ∆UL138STOP infection, which suggests this phenomenon occurs independently of UL138, as was observed for USP1." (PMID 41533576, 2026). "HSV1 USP was shown to deubiquitinate poly-ubiquitinated IκBα and mono-ubiquitinated PCNA to inhibit HSV1 DNA-induced IFN-β or NF-κB activation and DNA damage responses, respectively, to facilitate infection." (PMID 30764491, 2019). "Infection with the E2F1 expressing virus increased E2F1 protein and, as expected, the mRNA levels of the known E2F responsive genes, Cyclin E and PCNA." (PMID 28228757, 2017). "We looked at expression of Bloom (BLM), Proliferating Cell Nuclear Antigen (PCNA) and Mini-Chromosome Maintenance 4 (MCM4) at 16, 24, 48 and 72 h after infection as compared to mock infected cells." (PMID 29257057, 2017). "Lastly, induction of MCM4 lagged behind that of BLM and PCNA and correlated closely with initiation of viral DNA replication, with levels of MCM4 mRNA increasing at 48 h after infection in these cells." (PMID 29257057, 2017). "Protein-protein interaction analysis revealed that TGME49_120110 (PCNA), TGME49_049180 (DHFR-TS), TGME49_055320, and TGME49_002300 (ITPase) are the four hub genes with most interactions with T. gondii at the onset of infection." (PMID 27242740, 2016). "Overall, infection with dl309 induced expression of BLM, MCM4, and PCNA to levels higher than dl520 infection, and with the exception of PCNA to levels similar to those observed in pm975-infected cells." (PMID 26448631, 2015). "PCNA provides a molecular platform for substrate recognition by the CRL4Cdt2 E3-ubiquitin ligase and p21 targeting during MVM infection required its interaction both with Cdt2 and PCNA." (PMID 24699724, 2014). "PCNA is an important cofactor for MVM replication; it contributes to MVM replication in vitro, and is recruited to APAR bodies during infection." (PMID 24699724, 2014). "Jacob et al11 used PCR to detect the infection of HPV and immunohistochemistry to detect the PCNA expression in 41 patients with LSCC." (PMID 24353714, 2013). "Among the 71 cases, 31 (43.7%) showed infection of HPV and 38 (53.5%) showed overexpression of PCNA." (PMID 24353714, 2013). "Here we demonstrate that microglia increase expression of proliferating cell nuclear antigen (PCNA), and phenotypically express high levels of major histocompatibility complex (MHC)-Class I and II in response to acute infection with TMEV in SJL/J mice." (PMID 21494618, 2011). "Expression of PCNA by microglia isolated from sham- and TMEV-infected mice was analyzed at days 3, 5, and 7 post-infection." (PMID 21494618, 2011). "In contrast, non-ubiquitinated PCNA levels were maintained throughout either WT or ∆UL138STOP infection." (PMID 41533576, 2026). "Here, we observed that in the absence of UL138 protein, mUb–PCNA accumulated more rapidly and to greater levels than in WT infection (quantified in 4C)." (PMID 41533576, 2026). "USP1 depletion in ∆UL138STOP infection increased mUb–PCNA, but did not have a statistically significant effect on mUb–FANCD2 compared to the NTC control." (PMID 41533576, 2026). "Total PCNA levels decreased in mock-infected cells as cells grew to confluence, while total levels in HCMV-infected cells were maintained but decreased moderately at late times of infection, consistent with previous findings." (PMID 40130902, 2025). "In our study, PCNA knockdown in AD169 infection did not produce a significant change in virus replication." (PMID 40130902, 2025). "TRα1 GOF strongly increased the rate of cell proliferation compared to control-infection cells, while T3 treatment did not further change the percentage of PCNA-positive cells." (PMID 38693105, 2024). "Consistent with previous observations, PCNA is recruited to replicating viral DNA during infection (no inhibitor)." (PMID 37486931, 2023).